PAX6 (paired box 6)
Diseases named in the same sentence as PAX6 in open-access papers (continued):
Sharing a sentence is not in itself a finding about the gene and the disease.
aniridia (continued). "Single-strand conformation polymorphism analysis for exon 5 of PAX6 was performed to demonstrate co-segregation of the PAX6 mutation with aniridia in all family members and the absence of the mutation in the normal controls." (PMID 20664694, 2010). "The internal control was from a girl with typical aniridia and an identified c.718C>T (p.R240X) mutation in PAX6, suggesting the c.608G>A variation in SIX6 was unlikely to play a role in her ocular phenotype." (PMID 20057906, 2009). "Ten Catalan sheepdogs (6 affected and 4 non-affected) were tested for association of PAX6 with the aniridia phenotype." (PMID 17417604, 2007). "PAX6 was evaluated in dogs with an inherited form of aniridia, and sequence analysis indicated no pathological mutations in the coding regions or splice sites of aniridia-affected dogs, and Southern blot analysis showed no large deletions." (PMID 17417604, 2007). "Although PAX6 appears to be the major, and maybe even the only, gene involved in autosomal dominant aniridia, other aniridia clinical forms may be due to yet to be identified genes." (PMID 17417613, 2007). "Our genetic analysis provides further examples of PAX6 haploinsuffiency leading to aniridia." (PMID 16803629, 2006). "The absolute requirement for the presence of the DRR (or at least some of the enhancers within it) can explain why the aniridia phenotype in ‘position effect’ patients is indistinguishable from aniridia in patients carrying coding region mutations in PAX6." (PMID 17014839, 2006). "Pax6+/- mice represent an excellent model of human PAX6+/- aniridia-related keratopathy." (PMID 16914058, 2006). "Mutations in the PAX6 have so for been described in sporadic cases from India, but there was no previous report on mutations in Indian familial aniridia." (PMID 16803629, 2006). "In humans, heterozygous mutations of the PAX6 gene cause aniridia (absence of the iris) and related developmental eye diseases." (PMID 15918896, 2005). "Whilst there are reports implicating PAX6 in isolated juvenile open angle glaucoma and childhood glaucoma associated with Peters anomaly, childhood glaucoma caused by PAX6 variants is very rarely diagnosed in patients without aniridia." (PMID 41011222, 2025). "The broad protein distribution we observed across ocular tissues suggests that Pax6 insufficiency could impair multiple compartments simultaneously, explaining the wide spectrum of ocular phenotypes ranging from aniridia to microcornea, keratitis, and optic nerve anomalies." (PMID 41303332, 2025). "These emerging therapies, especially if combined with repurposed drugs and Pax6-enhancing agents, could significantly improve aniridia management, benefiting the over 7000 patients with congenital aniridia in the EU by offering rapid and accessible treatment options." (PMID 39518758, 2024). "Insufficient PAX6 levels, or haploinsufficiency, is thought to be the underlying genetic mechanism of aniridia; therefore, increasing full-length PAX6 levels, even if not fully, might be enough to attenuate disease." (PMID 37483273, 2023). "Here, we performed nanopore-based whole-genome sequencing to assess the presence of cryptic structural variants (SVs) on the only two unsolved “PAX6-negative” cases from a cohort of 110 patients with congenital aniridia after unsuccessfully short-read sequencing approaches." (PMID 37269011, 2023). "Notably, available ophthalmological data ruled out the presence of aniridia or other ocular defects that are observed in individuals with PAX6 mutations." (PMID 36202929, 2023). "Variants in the PAX6 gene account for >90% of all aniridia cases, regardless of whether they are familial (~66%) or sporadic (~33%)." (PMID 35327965, 2022). "This may imply that AS-OCT is the best tool to identify iris abnormalities associated with PAX6 mutations, and caution must be taken when drawing conclusions about a non-aniridia phenotype without using AS-OCT33." (PMID 32080308, 2020).
aniridia (continued). "Classically, PAX6 mutation is associated with an aniridia, but may also causes a variety of non-aniridia phenotypes such as microcornea, foveal hypoplasia, keratitis, and optic nerve malformations." (PMID 32080308, 2020). "Many researchers have noted that aniridia phenotypes are caused by mutations that introduce a PTC; however, they have also suggested that 3′ mutations, which introduce a PTC into the PAX6 open reading frame, do in fact yield dominant-negative alleles that may cause more severe phenotypes." (PMID 31341655, 2019). "However, since his aniridia is a consequence of an internal mutation within the PAX6 gene rather than a contiguous gene deletion including WT1, neither he nor his offspring will be at increased risk for the WAGR syndrome." (PMID 23799907, 2013). "The NR2E1 coding region, 5′ and 3′ untranslated regions (UTRs), exon flanking regions including consensus splice sites, and six evolutionarily conserved non-coding candidate regulatory regions were analyzed by sequencing 58 probands with aniridia of whom 42 were negative for PAX6 mutations." (PMID 23213277, 2012). "Further studies of the 17 families without PAX6 mutations may elucidate the molecular basis of aniridia in these families." (PMID 21850189, 2011). "However, the absence of PAX6 mutations in some cases of aniridia implies that mutations in additional genes cannot be excluded." (PMID 21850189, 2011). "In the ten cases that had no PAX6 mutation, only one had aniridia." (PMID 19898691, 2009). "Only one of the 12 cases without PAX6 mutation had aniridia." (PMID 19898691, 2009). "PAX6 gene mutations and polymorphisms identified in nine non-related Mexican aniridia cases." (PMID 18776953, 2008). "Unlike the structural agenesis seen in other factors, PAX6 mutations cause diabetes via a dual mechanism: reduced β-cell mass and a specific defect in proinsulin processing Patients classically present with aniridia (absence of the iris), which serves as an immediate diagnostic clue." (PMID 41614934, 2026). "The transcription factor PAX6 was significantly reduced at the mRNA level in IC samples from patients with EBMD, SND, pterygium, and congenital aniridia, measuring about half of the levels observed in controls (p = 0.016, p = 0.012, p = 0.02, p = 0.001)." (PMID 40094891, 2025). "Given that no PAX6 coding region mutation was identified on initial screening, the family was referred to our study to determine whether the break-point of this translocation could identify a novel locus or mechanism causing aniridia." (PMID 38050128, 2024). "Contiguous gene deletions of PAX6 and neighboring genes, such as WT1, are involved in a syndromic form of aniridia characterized by Wilms tumor, Aniridia, Genitourinary anomalies, and mental Retardation called WAGR syndrome." (PMID 37269011, 2023). "The human PAX6 gene was discovered during the search for the gene responsible for WAGR (Wilms tumor, aniridia, genital ridge defects, mental retardation) syndrome; patients with the syndrome often show a deletion in chromosome region 11p13." (PMID 35682795, 2022). "The human PAX6 gene was discovered in patients who suffer from WAGR syndrome (i.e., Wilms tumor, aniridia, genital ridge defects, mental retardation)." (PMID 35682795, 2022). "For those with sporadic aniridia, 33% of patients are diagnosed with WAGR syndrome, a contiguous gene deletion syndrome involving PAX6 and WT1." (PMID 34573386, 2021). "Consisting of Wilms tumor, aniridia, genitourinary abnormalities, and intellectual disability, WAGR syndrome is due to sporadic deletions of PAX6 and the contiguous WT1 (Davidoff, 2012; Szychot, Apps, & Pritchard‐Jones, 2014)." (PMID 32056389, 2020). "About 40–60% of patients with deletions encompassing both the PAX6 and WT1 genes develop WAGR syndrome (characterized by Wilms’ tumor, Aniridia, and Genitourinary abnormalities as well as mental Retardation) (OMIM #194072)." (PMID 32708836, 2020).
aniridia (continued). "Missense mutations in PAX6, which may lead to production of a full-length protein with altered structure and function, have been published associated with both classical aniridia and non-classical phenotypes." (PMID 30242502, 2019). "Large deletions that encompass PAX6 and other neighbour genes, such as WT1, result in systemic disease, such as WAGR, caracterised by the presence of Wilms tumour, aniridia, genitourinary anomalies, and retardation characterize (described in Section 6.2)." (PMID 31861090, 2019). "Human PAX6 was originally cloned from chromosomal locus 11p13, deletion of which is responsible for WAGR (Wilms tumor, Aniridia, Genital ridge defects, mental Retardation) syndrome." (PMID 27355350, 2016). "Therefore, the conversion from microRNA binding sites at the wild type PAX6 3′-UTR to coding region in the mutant, may abolish the regulation capacity of has-miR-365 and has-miR-375, and further elicit increased PAX6 mRNA expression, and consequently aniridia and high myopia." (PMID 22550392, 2012). "It is unclear whether the aniridia phenotype in the Turkish family is milder than that found in other patients, but it strongly suggests that the elements identified here, and/or other as yet unidentified distal enhancers, are essential to drive proper levels of Pax6 in the developing eye." (PMID 22220192, 2011). "There are several other genetic conditions that exhibit abnormal CCT measurements, including Marfan syndrome and aniridia, thus implicating the defective genes, fibrillin-1 (FBN1) and paired box 6 (PAX6), respectively, as potential modifiers of CCT." (PMID 20360993, 2010). "Finally, WAGR syndrome (OMIM 194072), which includes Wilms’ tumor, aniridia, genitourinary anomalies, and mental retardation, is caused by either microscopic or submicroscopic deletion of chromosome 11p13-p12 in a region containing both the Wilms tumor 1, WT1 gene and the PAX6 genes." (PMID 19862335, 2009). "The aim of this study was to determine the biometric properties of eyes affected by PAX6 haploinsufficiency-related classical congenital aniridia using a non-contact device." (PMID 41827221, 2026). "The siRNA-mediated knockdown model only partially replicates PAX6 haploinsufficiency and does not account for the genetic heterogeneity observed in patients with congenital aniridia." (PMID 40828815, 2025). "Subsequently, WES was performed in PAX6-negative samples to identify rarer phenotypes or those phenotypes overlapping with aniridia, especially in the neonatal period (n = 64)." (PMID 38459225, 2024). "Wilm's tumor, aniridia, genitourinary anomalies, and mental retardation (WAGR) syndrome is a contiguous gene deletion syndrome characterized by a denovo interstitial deletion on the p arm of chromosome 11, including the WT1 and PAX6 genes." (PMID 39600756, 2024). "Additionally, aniridia may present with systemic anomalies including Wilms tumor, genitourinary anomalies and mental retardation (WAGR syndrome), as deletions of 11p13 may encompass the Wilms tumor predisposition gene (WT1) which is located 700 kb beside the PAX6." (PMID 38594720, 2024). "Following comprehensive sequencing of the full-length PAX6 gene and its regulatory elements using targeted NGS approaches, we identified four DIVs in patients with congenital aniridia with no other potentially pathogenic SNVs or CNVs identified." (PMID 36675087, 2023). "Our results indicate that both rod and cone functions are affected and suggests that retinal changes in PAX6-related aniridia are not confined to the central macula." (PMID 37067366, 2023). "Previous studies showed that congenital aniridia (lack of an iris) in humans and murine small eye phenotypes, both arise from homologous defects in Pax6." (PMID 36215312, 2022). "We postulate that FOXC1-related aniridia appears to be the extreme end of iris hypoplasia rather than true aplasia as is seen in PAX6-related aniridia." (PMID 35327965, 2022).
aniridia (continued). "While the absence of one copy of PAX6 and WT1 is established as the cause for aniridia and Wilms tumour (and genitourinary anomalies), respectively, the genetic causes that are behind the neurodevelopmental defects are less clear." (PMID 31861090, 2019). "But the mutation, PAX6 c.1124C>G, is not co‐segregation from the aniridia and control of this family due to subject II2 with this mutation but without aniridia phenotype." (PMID 30334364, 2018). "Additionally, in a familial case of isolated aniridia (ANIRIDIA-052), the WAGR-array found a microdeletion of 63 Kb affecting exons 5a to 13 of PAX6, and also partially of the downstream ELP4 gene." (PMID 28231309, 2017). "Whole genome sequence analysis would be an attractive technique for the identification of novel causative mutations in the PAX6 region, and others involving new loci in PAX6-negative individuals with syndromic or isolated aniridia." (PMID 27124303, 2016). "This work emphasizes the necessity to screen for possible microdeletion related with PAX6 in patients with aniridia particularly when result of conventional sequencing analysis for PAX6 is negative." (PMID 25628759, 2015). "It is also possible that there are mutations in other genes which contribute to aniridia given that mutations in FOXC1 are associated with aniridia and that no PAX6 mutations were detected in aniridia patients with preserved visual function." (PMID 21850189, 2011). "Genome-wide copy number analysis of classic aniridia cases with negative PAX6 sequencing can investigate the first possibility." (PMID 21423868, 2011). "For example, Aniridia (absence of the iris) due to haloinsufficiency of PAX6 at 11q13 has been shown to result from a chromosomal rearrangement that disrupts the region downstream of PAX6 transcription unit." (PMID 21358991, 2010). "Human PAX6 gene is originally identified in chromosomal region 11p13 as one related with WAGR (Wilm's tumor, Aniridia, Genitourinary malformations and mental Retardation) syndrome, which is a rare genetic disorder caused by chromosomal deletion of the 11p12-p14 region." (PMID 21203536, 2010). "We found the c.969C>T nonsense substitution (Human PAX6 allelic database), which changes arginine 203 to a UGA stop codon in the linker region, in two unrelated probands (case 10 and case 24); both were sporadic aniridia cases." (PMID 18776953, 2008). "Chromosomal rearrangements disrupting the downstream cluster of ultraconserved transcriptional regulatory elements may affect PAX6 expression and can also induce a typical aniridia phenotype without a sequence change in PAX6 itself." (PMID 37542296, 2023). "For example, in a patient with the highly specific phenotype aniridia (AN1; OMIM: #106210; typically caused by a haploinsufficiency of PAX6) but with negative clinical genetic tests, a de novo SNV was identified in an ultra-conserved cis-element (SIMO enhancer) located 150 kb downstream from PAX6." (PMID 36672937, 2023). "However, direct RNA analysis is not feasible in patients with aniridia, given the specific expression of PAX6 in non-accessible tissues." (PMID 36675087, 2023). "While further evidence is needed to understand the role of the PAX6 deletion in human models, these emerging observations suggest that patients with WAGR, aniridia, and possibly other chromosome 11p13 related disorders may experience abnormal metabolism as they age." (PMID 34970513, 2021). "For these reasons, the PAX6 c.1124C>G most likely does not lead to congenital aniridia." (PMID 30334364, 2018). "It has long been postulated that germline mosaicism in healthy parents could be the most likely explanation for the exceptional disease recurrence in affected siblings with no family history of aniridia or PAX6-related microphthalmia." (PMID 30386378, 2018). "In this way, the percentage of patients with aniridia that appear not to carry PAX6 defects after routine genetic analysis could be probably reduced.." (PMID 28231309, 2017).
aniridia (continued). "Notably, loss of CK12 and CK10 expression has been noted in epithelial clones generated from Pax6-negative pannus tissue removed from the eyes of human patients with SQM resulting from aniridia and Stevens-Johnson syndrome." (PMID 24143217, 2013). "Here, we speculate that hidden SVs at the PAX6 locus might have been overlooked due to limitations of cytogenetic or short-read NGS technologies and, consequently, might partly explain some of the unsolved cases with congenital aniridia that remain to be genetically characterized." (PMID 37269011, 2023). "Two aniridia pedigrees have also been described in which deletion in the ELP4 gene region, not involving PAX6, was present in all subjects with aniridia but not in the investigated normal relatives." (PMID 21321669, 2011).